ULK3 (unc-51 like kinase 3)
Diseases named in the same sentence as ULK3 in open-access papers:
ULK3 is named in the same sentence as 36 diseases in open-access papers, as found by Europe PMC text mining. Sharing a sentence is not in itself a finding about the gene and the disease. The quoted sentences say what the papers report.
colon cancer (4 papers, 2013 to 2024). "We obtained the risk score of each case with colon cancer; risk score = (0.46121 × expression of ULK3) + (0.650715 × expression of ATG101) + (1.521474 × expression of MAP1LC3C) + (0.641122 × expression of TSC1) + (0.243022 × expression of DAPK1) + (-0.17015 × expression of SERPINA1)." (PMID 34315829, 2021). "Previous studies have identified the upregulation of ULK3 in squamous cell carcinoma of the skin and head and neck, and its potential as a prognostic biomarker in colon cancer." (PMID 39351539, 2024). "On the other hand, our analysis also revealed that suppression of SMO, HFU and ULK3 by external drug would be required to completely shut down the Hedgehog signaling in the colon cancer cell line." (PMID 23935937, 2013). "Besides, the staining level of DAPK1 and ULK3 were reduced in colon cancer." (PMID 34315829, 2021). "In case of Colon cancer scenario, we found that inhibition of SMO, HFU, ULK3 and RAS was useful to suppress the expressions of various responsive proteins of Hedgehog pathway." (PMID 23935937, 2013). "From our study we observed the under expressions of various oncoproteins in Hedgehog pathway while perturbing at a time the combinations of the proteins GLI1, GLI2 and SMO in Glioma; SMO, HFU, ULK3 and RAS in Colon cancer; SMO, HFU, ULK3, RAS and ERK12 in Pancreatic cancer." (PMID 23935937, 2013). "We identified 6 prognostic-related ARGs (ULK3, ATG101, MAP1LC3C, TSC1, DAPK1 and SERPINA1) to formulate a novel autophagy-related signature, which could stably predict the survival of patients and indicate the extent of immunosuppressive microenvironment in colon cancer." (PMID 34315829, 2021). "Therefore, we propose that in order to shut down the effect of Hedgehog signaling in colon cancer cell line for in-vitro or in-vivo analysis, one could also think a combination of drugs that will suppress the activity of SMO, HFU, ULK3 and RAS proteins altogether." (PMID 23935937, 2013).
squamous cell carcinoma (3 papers, 2021 to 2025). A carcinoma arising from squamous epithelial cells. "We show that ULK3 is a nuclear kinase with elevated expression levels in squamous cell carcinomas (SCCs) arising in multiple body sites, including skin and Head/Neck." (PMID 36797248, 2023). "In squamous cell carcinoma, inhibition of the ULK3 gene inhibits fibroblast effector gene expression as well as GLI2 activation, while inhibiting the growth-enhancing and oncogenic properties of these cells of neighboring cancer cells." (PMID 34168974, 2021).
breast carcinoma (2 papers, 2024). "However, there are currently no basic experimental research reports on the association between ULK3 and breast cancer." (PMID 39351539, 2024). "Decreased levels of CASP8, DDX58, CPNE1, ULK3, PARK7, and BTN2A1, as well as increased levels of TNFRSF9, TNXB, DNPH1, and TLR1, were linked to an elevated risk of breast cancer." (PMID 39351539, 2024). "Notably, fostamatinib, a spleen tyrosine kinase inhibitor used for chronic immune thrombocytopenia after other treatments, targets ULK3, which shows promise as a new therapeutic target for breast cancer treatment and as a prognostic biomarker." (PMID 39351539, 2024). "A preliminary SMR analysis conducted in the present study indicated a negative correlation between ULK3 and the risk of breast cancer." (PMID 39351539, 2024). "ULK3 has emerged from our study as a novel prognostic biomarker for breast cancer." (PMID 39351539, 2024). "Additionally, ULK3 showed promise as a prognostic biomarker for breast cancer." (PMID 39351539, 2024). "CASP8, DDX58, CPNE1, ULK3, PARK7, and TNFRSF9 have already been identified as targets in drug development and potential therapeutic targets for breast cancer treatment." (PMID 39351539, 2024).
Hypertension (2 papers, 2024). The presence of chronic increased pressure in the systemic arterial system. "The most significant association was observed between rs936228 (ULK3) and hypertension (P = 1 × 10-30)." (PMID 40027362, 2024). "After phenotype scanning, ULK3 and USP were found to be associated with hypertension, monocyte percentage of white cells and other vascular or heart problems." (PMID 38540773, 2024).
medulloblastoma (2 papers, 2022 to 2025). A malignant, invasive embryonal neoplasm arising from the cerebellum. "Indeed, combined depletion of Ulk3 and Stk36 resulted in more dramatic reduction of Hh pathway activity as well as Smo-driven medulloblastoma growth than depletion of either Ulk3 or Stk36 alone." (PMID 35186941, 2022).
actinic keratosis (1 paper, 2023). A precancerous lesion of the skin composed of atypical keratinocytes. "Pronounced nuclear accumulation of ULK3 was also found in actinic keratosis lesions, a pathological condition of major clinical significance that can evolve into SCC3,74, pointing to a role for this kinase in the early events of the keratinocyte transformation process." (PMID 36797248, 2023).
acute myeloid leukemia (1 paper, 2022). Acute myeloid leukemia (AML) is a group of neoplasms arising from precursor cells committed to the myeloid cell-line differentiation. "It promotes autophagy and proliferation of acute myeloid leukemia cells with mutant nucleophosphoprotein by regulating the expression of EGR1 and ULK3." (PMID 35299954, 2022).
bladder cancer (1 paper, 2021). "High expression of ULK3 is involved in bladder cancer and MTOR signaling pathway, among others." (PMID 34168974, 2021).
breast tumor (1 paper, 2021). "We also found that rs1869959 was associated the expression of ULK3 in breast tumor." (PMID 34234117, 2021).
cardiac ischemia (1 paper, 2024). "Two ULK3-targeting drugs were identified, one of which has gained approval for the treatment of chronic myeloid leukemia, while another has demonstrated potential in mitigating cardiac ischemia/reperfusion injury." (PMID 39526184, 2024).
epilepsy (1 paper, 2024). A brain disorder characterized by episodes of abnormally increased neuronal discharge resulting in transient episodes of sensory or motor neurological dysfunction, or psychic dysfunction. "This study employs a two-sample Mendelian randomization (MR) method to investigate the relationship between ULK3 and the risk of epilepsy." (PMID 39188705, 2024). "Observational studies have suggested that a multitude of pathological processes and biomolecules are involved in the initiation and development of epilepsy, and ULK3 is linked to the nervous system." (PMID 39188705, 2024). "Using bidirectional MR analysis, we explored the association between epilepsy and ULK3." (PMID 39188705, 2024). "Consequently, we conducted this study to assess the causal relationship between ULK3 and epilepsy, with the aim of improving epilepsy treatment strategies." (PMID 39188705, 2024). "However, it remains uncertain whether this association between ULK3 and epilepsy is causal and the direction of any causal relationship." (PMID 39188705, 2024). "Among these contributing factors, ULK3 is identified as potentially influential, particularly within specific types of epilepsy." (PMID 39188705, 2024). "To address the gaps in our understanding of the relationship between ULK3 and epilepsy, we conducted a two-sample MR analysis to investigate their causal connection." (PMID 39188705, 2024). "Nevertheless, further investigation is needed to understand the role of ULK3 in epilepsy fully." (PMID 39188705, 2024). "Heterogeneity and pleiotropy tests for bidirectional TSMR analyses between ULK3 and epilepsy." (PMID 39188705, 2024). "Recently, the role of ULK3 in epilepsy development remains unclear." (PMID 39188705, 2024). "In addition, the GWAS data in this study are based on results from a cross-sectional study, and longitudinal analysis of ULK3 and epilepsy is required to confirm our hypothesis." (PMID 39188705, 2024). "Besides, this study includes circulating levels of ULK3 protein, not protein levels in the brain or cerebrospinal fluid, which may be indirect for the assessment of epilepsy risk." (PMID 39188705, 2024).
esophageal cancer (1 paper, 2025). A primary or metastatic malignant neoplasm involving the esophagus. "Decreased levels of COL4A1, DEK, GINS1, HPCAL1, KIF4A and RBMX predicted longer survival in esophageal cancer patients, while overexpression of IGFL1P1, LRRC57A-AS1, SNHG3, ULK3 and ZFYVE19 correlated with longer survival." (PMID 41326355, 2025). "In contrast, IGFL1P1, LRRC57A-AS1, SNHG3, ULK3 and ZFYVE19 showed poor expression in esophageal cancer tissues but high expression in the combined treatment group." (PMID 41326355, 2025).
focal epilepsy (1 paper, 2024). A seizure caused by a localized disorder. "Our MR analyses revealed a causal relationship where an increased level of ULK3 was associated with a decreased risk of focal epilepsy (odds ratio = 0.92, 95% confidence interval: 0.86–1.00, p = 0.041)." (PMID 39188705, 2024). "In the forward MR analysis, we observed that a higher serum level of ULK3 was associated with a protective effect against focal epilepsy." (PMID 39188705, 2024). "This study suggests a causal relationship between ULK3 and the risk of focal epilepsy from a genetic perspective." (PMID 39188705, 2024). "We analyzed genome-wide association study (GWAS) summary statistics for ULK3 (sample size = 3,301), focal epilepsy (sample size = 39,348), and generalized epilepsy (sample size = 33,446)." (PMID 39188705, 2024). "Using the IVW method, we found a significant association between ULK3 and an increased risk of focal epilepsy (odds ratio (OR) = 0.924, 95% confidence interval (95% CI): 0.622–0.856, p = 0.041)." (PMID 39188705, 2024). "This study marks the first exploration of a causal relationship between ULK3 and focal epilepsy." (PMID 39188705, 2024). "Focal epilepsy (OR = 1.15, 95% CI: 0.471–0.963, p = 0.121) and generalized epilepsy (OR = 1.03, 95% CI: 0.510–0.933, p = 0.548) showed no significant causal effect on ULK3." (PMID 39188705, 2024). "However, in the reverse analysis, we found no significant causal effect of focal epilepsy on ULK3 (p > 0.05)." (PMID 39188705, 2024).
generalized epilepsy (1 paper, 2024). Epilepsy that is characterized by generalized seizure types and may have typical interictal and/or ictal EEG findings that accompany generalized seizure types (for example generalized spike-wave). "Using IVW, MR-Egger, weighted median, and weighted model methods, no significant causal relationship was found between ULK3 and the risk of generalized epilepsy (OR = 1.04, 95% CI: 0.727–0.952, p = 0.382)." (PMID 39188705, 2024). "Furthermore, no significant causation was identified between ULK3 and generalized epilepsy (p > 0.05)." (PMID 39188705, 2024). "However, we found no causal relationship between ULK3 and generalized epilepsy." (PMID 39188705, 2024).
glioblastoma (1 paper, 2021). The most malignant astrocytic tumor (WHO grade IV). "The promoter of autophagy-related gene ULK3 will promote the proliferation of NCoR-enriched glioblastoma cells." (PMID 33777735, 2021).
glioma (1 paper, 2013). A benign or malignant brain and spinal cord tumor that arises from glial cells (astrocytes, oligodendrocytes, ependymal cells). "Therefore to simulate the Glioma scenario in our study we considered the logical states of SHH, HFU, ULK3, ERK12, RAS, TWIST as “1” or “ON”." (PMID 23935937, 2013). "We also observed that HFU, ULK3, RAS, TWIST, ERK12 were functioning as sole activators on the other proteins in Glioma scenario (GS), but not in the Normal Scenario (NS)." (PMID 23935937, 2013).
immune thrombocytopenia (1 paper, 2024). "Fostamatinib, a spleen tyrosine kinase inhibitor, targets ULK3, providing therapeutic relief for chronic immune thrombocytopenia following alternative interventions." (PMID 39351539, 2024).
Impaired glucose tolerance (1 paper, 2024). An abnormal resistance to glucose, i.e., a reduction in the ability to maintain glucose levels in the blood stream within normal limits following oral or intravenous administration of glucose. "Additionally, KO models of JARID2, TRIO, and ULK3 exhibited homeostasis and metabolism phenotypes, including increased circulating creatine, decreased circulating magnesium, impaired glucose tolerance, and increased circulating cholesterol." (PMID 39526184, 2024).
leukemia (1 paper, 2021). A malignant (clonal) hematologic disorder, involving hematopoietic stem cells and characterized by the presence of primitive or atypical myeloid or lymphoid cells in the bone marrow and the blood. "Prompted by these findings, we further investigated the role of the downstream HOTAIRM1 target genes EGR1 and ULK3 in leukemia cells." (PMID 34615546, 2021). "Furthermore, nuclear HOTAIRM1 promoted EGR1 ubiquitination by enhancing the MDM2-EGR1 interaction, while cytoplasmic HOTAIRM1 increased ULK3 expression by competitively sponging miR-152-3p, therefore contributing to leukemia cell autophagy and proliferation." (PMID 34615546, 2021).
cancer (12 papers, 2016 to 2025). A tumor composed of atypical neoplastic, often pleomorphic cells that invade other tissues. "Consistent with our findings, a more recent study showed that Ulk3 formed a complex with Gli2 in the nucleus in cancer-associated fibroblasts." (PMID 39792672, 2025). "ULK3 is upregulated in cancer-associated fibroblasts (CAFs) derived from head and neck squamous cell carcinomas, prostate cancer, and breast cancer." (PMID 36674464, 2023). "Up-regulation of ULK3 is involved in cancer-associated fibroblasts transformation and induces autophagy." (PMID 34315829, 2021). "ULK3 connects two key signaling pathways in the transformation of normal fibroblasts into cancer-associated fibroblasts and, therefore, may represent a potential target for cancer therapy." (PMID 33126898, 2020). "In vivo, ULK3 inhibition reduced MM burden, improved survival, and protected against cancer-induced bone disease." (PMID 40831505, 2025). "Although little is known about ULK3 in cancer, studies on its Drosophila ortholog, ADUK, suggest that it plays a key role in autophagy initiation upon chemotherapy-induced stress." (PMID 40831505, 2025). "Because ULK3 is critical for CAF conversion for the pro-tumorigenic properties on neighboring cancer cells, it is a promising target for suppressing CAF activation and its tumor enhancement effects." (PMID 36674464, 2023). "Other reports have linked ULK3 to the expression of oncogenes such as GLI2, which induces the expression of anti-apoptotic proteins, again tying in with the role of autophagy in cancer cell survival." (PMID 40831505, 2025). "ULK3 has also been implicated in oncogenic pathways including its interaction with GLI2, which regulates anti-apoptotic proteins such as BCL-2, linking autophagy to cell survival in certain cancers." (PMID 40831505, 2025). "Targeting ULK3 represents a promising therapeutic strategy, particularly in resistant disease settings, and provides a foundation for future drug development efforts focused on autophagy-dependent cancers." (PMID 40831505, 2025). "Molecular analysis showed that, particularly in early AK lesions, FGFR2c dermal upregulation is accompanied by the downregulation of the cancer-associated fibroblasts (CAF) transcription repressor CSL, the upregulation of the CAF activator ULK3, and the consequent CAF gene induction." (PMID 36979155, 2023). "By using the search function of the CancerSplicingQTL database, it was found that splicing events such as ULK3_AD_31756, NDUFS5_AD_1869, and MRPL43_AD_12856 were significantly correlated with the corresponding SNPs rs12898397, rs2863095, and rs1122472 respectively in most of the analyzed cancers." (PMID 37810965, 2023). "Indeed, recent studies in skeletal muscle and cancer cells reported that pharmacological activation of REV-ERBα inhibits autophagosome formation via negative modulation of core autophagy genes such as Ulk3, Ulk1, Bec1, Atg7, and Atg5." (PMID 35428762, 2022).
tumor (8 papers, 2015 to 2025). "Using the small molecule inhibitor MA9, we demonstrate that ULK3 activity can be effectively blocked at nanomolar concentrations, leading to a reduction in MM tumor burden, preservation of bone integrity, and improved overall survival in vivo." (PMID 40831505, 2025). "Even in this case, tumors formed by SCC cells with ULK3 silencing were significantly smaller than those derived from control cells, with tumor growth being suppressed entirely in some animals." (PMID 36797248, 2023). "Upregulation of the ULK3 gene is known to occur in several tumor types, and ULK3 silencing suppresses tumor progression." (PMID 33126898, 2020). "The identification of ULK3 as an essential component of the abscission checkpoint, thus, opens a new avenue in the emerging relationship between the abscission checkpoint and tumor formation." (PMID 26011858, 2015). "The findings are likely of functional significance, as ULK3 targeting decreased HKC and SCC proliferative potential, promoting differentiation and limiting tumor growth." (PMID 36797248, 2023). "The results reported so far are in line with previous findings, reporting the pivotal role of CSL/ULK3 negative loop in the simultaneous regulation of autophagy and CAF program activation, both events required for tumor-enhancing properties of stromal cells." (PMID 36979155, 2023).
cardiovascular disease (2 papers, 2020 to 2024). "However, limited information exists regarding the association between ULK3 and cardiovascular disease as well as CAC." (PMID 39526184, 2024). "Noteworthy, our results do not support the previously identified genetic relationship of AMD and cardiovascular disease (CAD), as only a single AMD-associated gene (ULK3) overlaps with an R2 locus of CAD16,56." (PMID 32005911, 2020).
infection (2 papers, 2022 to 2023). The state of being infected such as from the introduction of a foreign agent such as serum, vaccine, antigenic substance or organism. "To eliminate the issue of individual clone variability and possible compensatory mutations resulting from ULK3 loss, we analyzed pooled polyclonal cell populations shortly selected after infection with lentiviruses co-expressing Cas9 together with ULK3-targeting guide RNAs (gRNAs)." (PMID 36797248, 2023). "A similar transcriptomic analysis was performed with SCC13 cells plus/minus ULK3 gene silencing by infection with two shRNA lentiviral vectors (GSE1830850)." (PMID 36797248, 2023). "For further mechanistic insights, we performed a global transcriptomic analysis of three HKC strains in which the ULK3 gene was silenced by infection with two different lentiviruses versus empty vector control." (PMID 36797248, 2023). "Flow cytometry results show that siRNA silencing the expression of SGK3, ULK3, ERBB4, STK17B can reduce the infection efficiency of ORFV-GFP virus, while siRNA silencing the expression of MST1R, PAK4, ERBB3 can increase the infection of ORFV-GFP virus efficient." (PMID 35401439, 2022).
neurodevelopmental disorder (1 paper, 2025). A behavioral and cognitive disorder with onset during the developmental period that involves impaired or aberrant development of intellectual, motor, or social functions. "In contrast, ULK3 and FYN, key regulators of neuronal development and potential therapeutic targets for neurodevelopmental disorders, were upregulated at the protein level." (PMID 40568166, 2025).
ULK3 also shares sentences with these, for which no sentence is quoted: cervical cancer (1 paper); chronic myeloid leukemia (1); cytomegalovirus infection (1); influenza (1); multiple myeloma (1); pancreatic cancer (1); prostate carcinoma (1); prostate tumor (1); rhabdomyosarcoma (1); schizophrenia (1); skin cancer (1); squamous cell carcinoma of the skin (1).